ENO1 (enolase 1)
Diseases named in the same sentence as ENO1 in open-access papers (continued):
Sharing a sentence is not in itself a finding about the gene and the disease.
lung fibrosis (2 papers, 2015 to 2023). "In bleomycin-treated mice (harvested on day 21), which is commonly used pulmonary fibrosis animal model, elevated expression of ENO1 in lungs was also observed compared to those from the sham group." (PMID 37964270, 2023). "This study demonstrates that surface ENO1 regulates cell trafficking, inflammatory mediators, and fibrotic mediators involving various pathological cell populations in pulmonary fibrosis." (PMID 37964270, 2023). "To explore ENO1 expression in the context of pulmonary fibrosis, we performed ENO1 immunohistochemistry (IHC) staining in commercially available formalin-fixed paraffin-embedded (FFPE) human tissue sections of normal and fibrotic lungs." (PMID 37964270, 2023). "In agreement, our results further support the pathologic roles of extracellular/cell surface ENO1 in mediating lung fibrosis." (PMID 37964270, 2023). "Our results would provide a rationale to develop ENO1 blocking antibody for treating pulmonary fibrosis." (PMID 37964270, 2023). "Nevertheless, this study is the first to suggest ENO1 Ab with therapeutic potential for pulmonary fibrosis." (PMID 37964270, 2023). "Since fibroblast recruitment in response to lung injury also leads to fibrosis, we therefore hypothesized ENO1 might possess pro-fibrotic effects via facilitating monocytes and fibroblasts trafficking in lung fibrosis." (PMID 37964270, 2023). "Taken together, our results indicated pro-inflammatory and pro-fibrotic roles of cell surface (or extracellular) ENO1 in pulmonary fibrosis, which might provide rationales to explain the efficacy of HL217 observed in bleomycin-treated fibrotic mice." (PMID 37964270, 2023). "In brief, targeting ENO1 by our proprietary antibody HL217 ameliorates bleomycin-induced pulmonary fibrosis in vivo as evidenced by the attenuation of fibrosis (i.e., collagen deposition in lungs), TGF-β reduction in BALF, and immune cells infiltration in lungs." (PMID 37964270, 2023). "The results suggested protective effects of ENO1 blocking Ab in pulmonary fibrosis." (PMID 37964270, 2023). "To test our hypothesis again that surface ENO1-mediated cell migration of the involved lung fibroblasts is intrinsic and crucial in the development of pulmonary fibrosis, we investigated the in vitro effect of HL217 on the migration ability of primary human lung fibroblasts." (PMID 37964270, 2023). "We could reason and speculate that the target cells of ENO1 Ab HL217 are endothelial cells, neutrophils, circulating monocytes, alveolar macrophages, and lung fibroblasts/myofibroblasts in the context of pulmonary fibrosis." (PMID 37964270, 2023). "Although our results clearly indicate the involvement of surface ENO1 in bleomycin-induced lung fibrosis, we have not optimized the dosing schedule of HL217 as a “treatment” protocol." (PMID 37964270, 2023). "Since ENO1 has been reported to promote fibrosis, we herein tested if our proprietary ENO1 Ab (HL217) could reduce fibrosis in the murine model of bleomycin-induced pulmonary fibrosis." (PMID 37964270, 2023). "Moreover, in primary ATII cells from bleomycin-induced lung injury – a model exhibiting activated Wnt/β-catenin signaling and pulmonary fibrosis in vivo – CBR2 expression was reduced, significantly correlating with reduced pro-SFTPC, whereas ENO1, PDIA3 and T1α were increased." (PMID 26035385, 2015).
Miscarriage (2 papers, 2022 to 2023). A pregnancy that ends at a stage in which the fetus is incapable of surviving on its own, defined as the spontaneous loss of a fetus before the 22th week of pregnancy. "Another recent in vitro study has shown that ENO1-specific IgG could directly reduce β-hCG and progesterone production of cultured trophoblast cells, indicating a potential mechanism of causing miscarriage." (PMID 36674531, 2023). "The highly expressed ENO1-P6Abs may be important risk factors for euthyroid TAI-related miscarriage." (PMID 35707546, 2022). "We acknowledge that we have not completed the investigation of the mechanisms of ENO1-P6Abs in the development of AIT-related miscarriage, so their cause–effect relationship awaits further study in the future." (PMID 36674531, 2023). "The findings in this pilot study could help to develop new clinical prediction and treatment strategies for AIT-related miscarriage based on ENO1Ab expression, especially those against the related specific epitopes of ENO1." (PMID 36674531, 2023). "However, a large-sample clinical investigation and a series of experimental studies need to be performed to further verify our findings and to establish the cause–effect relationship between ENO1-P6Ab expression and AIT-related miscarriage." (PMID 36674531, 2023). "However, the AUC (0.674) from ROC analysis only showed a fair diagnostic value with moderate accuracy, which further reminds us of exploring the specific antigen epitope of ENO1 involved in AIT-related miscarriage." (PMID 36674531, 2023). "The constructive expression of ENO1 in the placenta and increased production of P6Abs in AIT women suffering from miscarriage suggest that ENO1-P6Ab might injure the placenta and embryo through ADCC and/or CDC." (PMID 36674531, 2023). "Interestingly, only the serum level of total IgG against P6 epitope of ENO1 (aa 168–183) was significantly increased in the AIT miscarriage group compared with that of the AIT non-miscarriage group." (PMID 36674531, 2023). "Meanwhile, overexpressed ENO1 protein was found in the decidua of patients who had undergone a miscarriage, and ENO1Ab could directly recognize trophoblast cells and inhibit hormone secretion." (PMID 36674531, 2023). "This study suggests serum ENO1Ab might have a fair predictive value for AIT-related miscarriage, and especially ENO1-P6Ab may be more specifically related to this disorder." (PMID 36674531, 2023). "In this study, we have performed a series of analyses to explore whether the Abs against the epitope aa 168–183 of the ENO1 protein (P6) were involved in the development of TAI-related miscarriage." (PMID 35707546, 2022). "Binary logistic regression analysis of the potential risk factors for miscarriage without ENO1-P6Abs included among the euthyroid TAI women." (PMID 35707546, 2022). "The findings indicate that ENO1-P6Abs may play a critical role in the pathogenesis of TAI-related pregnancy loss and may become the predictive markers for TAI-related miscarriage." (PMID 35707546, 2022). "However, the target epitopes of ENO1 specific to miscarriage due to various causes have not been investigated yet." (PMID 35707546, 2022). "In this study, we explored the potential roles of ENO1Ab in miscarriage occurrence among AIT women, and the specific epitopes of ENO1 targeted by ENO1Ab." (PMID 36674531, 2023). "Therefore, we infer that the direct binding of ENO1-P6Abs to the epitope may inhibit the glycolysis process, reduce the energy supply to the placenta and the embryo, and finally contribute to the occurrence of miscarriage." (PMID 35707546, 2022). "The serum total IgG against ENO1 was significantly higher in the women with miscarriage than in those without miscarriage (p < 0.001)." (PMID 36674531, 2023). "ENO1-P6Abs, especially its IgG2 subclass, may be used as a new predictive biomarker for TAI-related miscarriage." (PMID 35707546, 2022).
Miscarriage (continued). "There are only a few studies on disease-specific epitopes (DSEs) of ENO1 as an autoantigen, and no investigation has been reported on either miscarriage or TAI." (PMID 35707546, 2022). "Additionally, we did not explore the related mechanisms for ENO1-P6Abs to be involved in the development of TAI-related miscarriage in this study." (PMID 35707546, 2022). "The serum level of total IgG against the predicted epitope peptide 6 (i.e., P6 and aa168-183) of ENO1 was significantly increased in women with AIT and miscarriage when compared with those of both the AIT non-miscarriage group and non-AIT miscarriage group." (PMID 36674531, 2023).
Myocardial fibrosis (2 papers, 2023 to 2025). "Inhibition of transcriptional activation of ENO1 was able to reduce glycolysis and prevent myocardial fibrosis after MI, among others." (PMID 37938421, 2023).
Obesity (2 papers, 2024 to 2025). Accumulation of substantial excess body fat. "In this regard, ENO1 downregulation have been associated with weight regain in patients with obesity who followed a weight loss program, indicating the role of ENO1 expression changes on finding target for preventing weight regain and treat metabolic disorders." (PMID 38703299, 2024). "Previous studies in obesity have reported decreased levels of ENO1 in adults with obesity and T2DM." (PMID 38703299, 2024).
peripheral T-cell lymphoma (2 papers, 2022 to 2024). "In peripheral T-cell lymphoma, high ENO1 expression in tissues is positively correlated with low overall survival rates." (PMID 38840205, 2024).
pneumonia (2 papers, 2022 to 2023). An acute, acute and chronic, or chronic inflammation focally or diffusely affecting the lung parenchyma, caused by an infection in one or both of the lungs (by bacteria, viruses, fungi, or mycoplasma.). "Increased surface ENO1 expression on monocytes were found in patients with pneumonia, and overexpression of an ENO1 variant lacking its plasminogen binding site attenuated migration of monocytes into the inflamed lungs in mice." (PMID 37964270, 2023). "For instance, ENO1 facilitated lipopolysaccharide (LPS)-driven monocyte recruitment to the acutely inflamed lung, and ENO1 was highly expressed in blood monocyte cell surface and alveolar mononuclear cells of patients with pneumonia." (PMID 36387401, 2022).
prostate adenocarcinoma (2 papers, 2021 to 2022). "We showed here that ENO1 is specifically localized to the invadopodial surface of a significant subset (11.1%-63.9%) of CSCs in human gastric and prostate adenocarcinomas." (PMID 34136381, 2021).
psoriasis (2 papers, 2023 to 2026). An autoimmune condition characterized by red, well-delineated plaques with silvery scales that are usually on the extensor surfaces and scalp. "Machine learning pinpointed MPHOSPH6, ENO1, MKI67, and FABP5 as lactylation-related biomarkers for psoriasis, with ROC curves confirming their strong diagnostic capabilities." (PMID 41909697, 2026). "This study aimed to evaluate the relationship between ENO1 and K17 in promoting the development of psoriasis." (PMID 37497003, 2023). "In our study, we found that ENO1 directly regulates KCs proliferation in psoriasis by interacting with K17." (PMID 37497003, 2023). "Immunofluorescence, Western blotting, RT‒qPCR and IHC staining showed that ENO1 expression was dramatically increased in the epidermis of psoriasis patients compared to normal controls." (PMID 37497003, 2023). "In vitro experiments and animal models confirmed that ENO1 was involved in regulating glycolysis and cell proliferation, thus contributing to the development of psoriasis." (PMID 37497003, 2023). "Collectively, these data document that ENO1 modulates the phosphorylation of K17, which further contributes to the glycolysis and proliferation of KCs in psoriasis." (PMID 37497003, 2023). "In summary, our study revealed the mechanism by which K17 interacts with ENO1 to promote glycolysis and proliferation of KCs, mediating the occurrence and development of psoriasis." (PMID 37497003, 2023). "Taken together, our results indicate that the interaction of K17 and ENO1 boosts the glycolysis and proliferation of KCs and accelerates the process of psoriasis development." (PMID 37497003, 2023). "Altogether, our results suggest that ENO1 directly regulates glycolysis and the proliferation of KCs, thus exacerbating the development of psoriasis." (PMID 37497003, 2023). "Taken together, these data indicate that K17 can directly induce elevated expression and activation of ENO1 in psoriasis." (PMID 37497003, 2023). "Finally, either inhibiting the expression and activation of ENO1 or repressing K17-Ser44 phosphorylation significantly alleviated the IMQ-induced psoriasis-like phenotype in vivo." (PMID 37497003, 2023). "Finally, using an IMQ-induced psoriasis-like mouse model, we confirmed that inhibiting either the expression or activity of ENO1 alleviated the severity of psoriasis." (PMID 37497003, 2023). "Thus, we conclude that ENO1 can directly regulate K17 phosphorylation with independence of RSK1 in psoriasis." (PMID 37497003, 2023). "Next, to investigate whether ENO1 participates in the development of psoriasis, we detected the expression of ENO1 in lesions from psoriasis patients." (PMID 37497003, 2023). "Meanwhile, the excessive expression of ENO1 maintains the phosphorylation of K17-Ser44, and phosphorylated K17 functions as a transcription factor to promote the glycolysis and proliferation of KCs in psoriasis." (PMID 37497003, 2023). "RT‒qPCR results showed that KCs from psoriasis patients expressed higher mRNA levels of glycolytic transporters (GLUT1) and glycolytic enzymes (PFKM, LDHA, HK2, PKM2, ENO1 and PGK1) than those from healthy skin." (PMID 37497003, 2023). "Consistently, RT‒qPCR results showed that K17 KO also downregulated the mRNA levels of the proliferation markers K17, K16, PCNA, Cyclin D1 and key enzymes (GLUT1, PFKM, LDHA, HK2, PKM2, ENO1 and PGK1) in the IMQ-induced psoriasis-like model." (PMID 37497003, 2023). "Conversely, ENO1 regulates and maintains the phosphorylation of K17, which further acts as a transcription factor to promote the transcription of LDHA, amplifying the glycolysis process and leading to hyperproliferation of KCs in psoriasis." (PMID 37497003, 2023). "To explore the effect of ENO1 on KCs dysfunction in psoriasis, we established KC models with ENO1 silencing using siRNA or inhibition by an ENO1 inhibitor (ENOBlock, a nonenzymatic active site inhibitor of ENO1)." (PMID 37497003, 2023).
psoriasis (continued). "Moreover, Ki67 expression and the mRNA levels of proliferation markers K17, K16, PCNA, Cyclin D1 and key enzymes (GLUT1, PFKM, LDHA, HK2, PKM2, ENO1 and PGK1) were also decreased in epidermal KCs of the IMQ-induced psoriasis-like model with local application of BI-D1870." (PMID 37497003, 2023). "However, the physiological and pathological roles of ENO1 in psoriasis have not yet been fully elucidated, and whether ENO1 and K17 act together to contribute to abnormal glycolysis and excessive proliferation of KCs in psoriasis has not previously been examined." (PMID 37497003, 2023).
pulmonary arterial hypertension (2 papers, 2022 to 2025). Pulmonary arterial hypertension (PAH) is a group of diseases characterized by mean pulmonary artery pressure >20 mmHg and elevated pulmonary arterial resistance leading to right heart failure. "α-Enolase (ENO1) has been implicated in pulmonary artery smooth muscle cell hyperproliferation in pulmonary hypertension." (PMID 35204311, 2022). "The pharmacologic inhibition of ENO1 led to decreases in the glycolytic switch under hypoxic conditions, and pharmacologic inhibition reversed pulmonary hypertension in animal models." (PMID 35204311, 2022).
pulmonary hypertension (2 papers, 2022). Increased pressure within the pulmonary circulation due to lung or heart disorder. "Among them, ENO1 and IDH1 were demonstrated to be aberrantly expressed in pulmonary hypertension, which provided strong support for our results." (PMID 35646965, 2022).
rectal cancer (2 papers, 2023 to 2024). A primary or metastatic malignant neoplasm that affects the rectum. "The results indicated that TYRO3 expression was positively associated with ENO1 expression in colon and rectal cancer tissues from TCGA database." (PMID 37116196, 2023). "The ENO1 K420cr mutant shows more vigorous ENO1 activity than wild-type ENO1 and can promote lactate production inside and outside rectal cancer cells." (PMID 39513918, 2024).
schizophrenia (2 papers, 2019 to 2024). A major psychotic disorder characterized by abnormalities in the perception or expression of reality. "Another investigation using samples of post mortem hippocampus of patients with schizophrenia found that glycolysis- and gluconeogenesis-associated proteins were altered, as seen by decreased levels of ALDOC and increased ENO1." (PMID 30890939, 2019). "In glycolysis, the gene ENO1 showed a discordant expression pattern between the two groups (i.e., ENO1 was upregulated in schizophrenia and downregulated in ketosis), whereas the genes GAPDH and PFKP showed a concordant expression pattern, being downregulated in both states." (PMID 39125835, 2024).
small cell lung carcinoma (2 papers, 2014 to 2024). Small cell lung cancer (SCLC) is a highly aggressive malignant neoplasm, accounting for 10-15% of lung cancer cases, characterized byrapid growth, and early metastasis. "MA treatment of small cell lung carcinoma DMS114 cells caused downregulation of glycolytic proteins (ALDOA, GAPDH, ENO1, PyKM2 and LDHA) as well as upregulation of OxPhos proteins (cytochrome b-c1 complex subunit 2 and cytochrome c oxidase subunit 5B)." (PMID 39288141, 2024).
Acute Myeloid Leukaemia (1 paper, 2024). "Although ENO1 is one of the most highly expressed genes in acute myeloid leukaemia (AML), its potential role as a biomarker in AML or its precursor, myelodysplastic neoplasms (MDS), has not been investigated." (PMID 38473245, 2024).
acute rheumatic fever (1 paper, 2018). "The cross-reactivity between bacterial enolase and ENO1 was first reported in association with acute rheumatic fever after Group A streptococcal infection." (PMID 30001173, 2018).
asthenozoospermia (1 paper, 2024). "Histone H4, cathepsin L, glutathione synthetase, and ENO1 emerged as potential biomarkers for asthenozoospermia." (PMID 38605082, 2024). "Furthermore, proteins histone H4, cathepsin L, glutathione synthetase and ENO1 are proposed as potential biomarkers of autophagy and vitality in asthenozoospermia sperm." (PMID 38605082, 2024).
autism (1 paper, 2023). Persistent deficits in social interaction and communication and interaction as well as a markedly restricted repertoire of activity and interest as well as repetitive patterns of behavior. "For instance, we showed that ENO1 and ALDOA interact with MED13, which has been associated with a broad range of NDDs including encephalopathy, intellectual disability, and autism." (PMID 37664457, 2023).
autoimmune retinopathy (1 paper, 2020). An autoimmune disease characterized by sudden onset of photopsias and scotomata in patients with no family history of retinitis pigmentosa, followed by visual field and central vision loss. "Further, the survival of retinal cells treated with ENO1 autoantibodies from patients with autoimmune retinopathy and CAR was impaired compared to retinal cells exposed to sera from healthy controls." (PMID 33584813, 2020). "ENO1 autoantibodies from patients with autoimmune retinopathy also target retinal ganglion cells and induce apoptosis in rats." (PMID 33584813, 2020).
bipolar disorder (1 paper, 2024). A disorder of the brain that causes unusual shifts in mood, energy, activity levels and the ability to carry out day-to-day tasks. "ENO1, PFKP, and GAPDH were also downregulated in bipolar disorder with a similar magnitude of expression change in both states." (PMID 39125835, 2024).
bone marrow failure (1 paper, 2024). "Taken together, it could be speculated that ENO1 may be a marker of bone marrow dysfunction in these malignancies and could have a potential use as a biomarker for early detection of bone marrow failure preceding numerous hematologic diseases." (PMID 38473245, 2024).